RPS6KA2 (ribosomal protein S6 kinase A2)
Description:
Serine/threonine-protein kinase that acts downstream of ERK (MAPK1/ERK2 and MAPK3/ERK1) signaling and mediates mitogenic and stress-induced activation of transcription factors, regulates translation, and mediates cellular proliferation, survival, and differentiation. May function as tumor suppressor in epithelial ovarian cancer cells.
Synonyms: p90RSK2; MAPKAPK1C; RSK3; HU-2; RSK; S6K-alpha; S6K-alpha2; p90-RSK3; pp90RSK3
Tractability: Small molecule: a drug acting on it is in phase 1 trials; a high-quality ligand is known; it belongs to a druggable protein family. PROTAC: ubiquitination databases record sites on it; its protein half-life has been measured; a small molecule that binds it is known.
Target class: Enzyme; Kinase; AGC protein kinase group; AGC protein kinase RSK subfamily; Protein Kinase; AGC protein kinase RSK family
Chemical probes: BI-D1870, BI00645435 (high quality), PD080917
Gene: Protein-coding gene on chromosome 6 (166,409,364 to 166,906,451, reverse strand). Ensembl gene ENSG00000071242.
Subcellular location: Nucleus; Cytoplasm
Subcellular location (Human Protein Atlas): Nucleoplasm
Pathways (Reactome):
Signal Transduction: CREB phosphorylation; ERK/MAPK targets; Gastrin-CREB signalling pathway via PKC and MAPK
Neuronal System: CREB1 phosphorylation through NMDA receptor-mediated activation of RAS signaling; RSK activation
Cellular responses to stimuli: Senescence-Associated Secretory Phenotype (SASP)
Developmental Biology: Recycling pathway of L1
Gene Ontology:
Molecular function: protein binding; protein serine/threonine/tyrosine kinase activity; protein serine/threonine kinase activity; ribosomal protein S6 kinase activity; ATP binding; magnesium ion binding; protein kinase activity; protein serine kinase activity
Biological process: negative regulation of cell cycle; negative regulation of cell population proliferation; positive regulation of apoptotic process; chemical synaptic transmission; intracellular signal transduction; signal transduction; TORC1 signaling
Cellular component: cytoplasm; nucleoplasm; nucleus; cytosol; meiotic spindle; spindle; synapse
Genetic constraint (gnomAD): Loss-of-function variants: 29 observed, 63.33 expected, observed/expected ratio (o/e) 0.46, 90% interval 0.34 to 0.62. The upper end of that interval is the gene's LOEUF score, 0.62, which puts it in group 2 of 6, group 1 being the genes least tolerant of losing a copy. Missense variants: 605 observed, 747.29 expected, observed/expected ratio (o/e) 0.81, 90% interval 0.76 to 0.87. Synonymous variants: 337 observed, 304.97 expected, observed/expected ratio (o/e) 1.11, 90% interval 1.01 to 1.21.
Homologues: Orthologues: guinea pig RPS6KA2 (96% identical), chimpanzee RPS6KA2 (96% identical), mouse Rps6ka2 (96% identical), macaque RPS6KA2 (95% identical), dog RPS6KA2 (93% identical), rat Rps6ka2 (92% identical), pig RPS6KA2 (92% identical), zebrafish rps6ka2 (89% identical), tropical clawed frog rps6ka2 (87% identical), rabbit RPS6KA2 (84% identical), Caenorhabditis elegans rskn-2 (37% identical), Drosophila melanogaster JIL-1 (34% identical), and 4 more. Paralogues in human: RPS6KA3 (81% identical), RPS6KA1 (77% identical), RPS6KA6 (74% identical), RPS6KA5 (43% identical), RPS6KA4 (41% identical), RPS6KB1 (31% identical), RPS6KB2 (28% identical).
Diseases named in the same sentence as RPS6KA2 in open-access papers:
RPS6KA2 is named in the same sentence as 42 diseases in open-access papers, as found by Europe PMC text mining. Sharing a sentence is not in itself a finding about the gene and the disease. The quoted sentences say what the papers report.
breast carcinoma (16 papers, 2013 to 2025). "Accumulating data further suggest that RPS6KA2 plays a role in the emergence of resistance to tamoxifen in breast cancer, as well as to various other targeted treatments." (PMID 41502518, 2025). "Tightly positive correlations of mRNA levels between JUND and RPS6KA2 were observed in different subtypes of breast cancer." (PMID 31937753, 2020). "Ribosomal protein S6 kinase A2 (RPS6KA2) has been identified as a potential prognostic biomarker in several cancers, including breast cancer, glioblastoma, and prostate cancer." (PMID 41502518, 2025). "A screen with active kinases in HMECs upon TGFβ treatment identified that the serine threonine kinase RSK3, or RPS6KA2, a kinase mainly known to regulate cancer cell death including in breast cancer, reverted TGFβ-induced senescence." (PMID 38008756, 2023). "Our data support that an underexplored kinase, RPSK6A2 (Ribosomal Protein S6 Kinase A2) also known as RSK3, inhibits TGFβ-induced senescence and promotes malignant progression of breast cancer." (PMID 38008756, 2023). "Firstly, overexpression of ribosomal S6 kinases RPS6KA2 (RSK3) and RPS6KA6 (RSK4) promoted breast cancer growth upon PI3K inhibition treatment, which can be reversed by addition of MEK- or RSK-specific inhibitors." (PMID 33790792, 2021). "Ectopic expression of FOXD3 stimulated the expression of miR-548d-3p and repressed JUND and RPS6KA2 mRNA expression, as well as greatly enhancing the BET sensitivity of luminal breast cancer cells." (PMID 31937753, 2020). "Lastly, to further confirm the role of JunD/RSK3 signalling in BET resistance, RPS6KA2 and JUND were respectively knocked down in two JQ1-resistant breast cancer cell lines (BT474 and MDA-MB-453), and showed that the silencing of both RPS6KA2 and JUND restored the JQ1 sensitivity of these cells." (PMID 31937753, 2020). "The ribosomal protein S6 kinase A2 (RPS6KA2) functions as a tumor suppressor gene and is commonly subject to deletion or downregulation, with studies identifying its abnormal expression as a potential marker of poor prognosis in breast cancer, glioblastoma, and prostate cancer." (PMID 41502518, 2025).
ovarian carcinoma (10 papers, 2016 to 2025). A malignant neoplasm originating from the surface ovarian epithelium. "Simultaneous targeting of RPS6KA2 and the associated autophagy-ferroptosis signaling networks markedly increases the responsiveness of ovarian cancer cells to cisplatin." (PMID 41502518, 2025). "In breast and ovarian cancers, a higher expression of RPS6KA2 has been associated with a worse prognosis, suggesting that this gene functions as an oncogene." (PMID 36883564, 2023). "Furthermore, this study investigated the relationship between RPS6KA2 expression and key signaling pathways associated with cell proliferation and apoptosis in ovarian cancer." (PMID 41502518, 2025). "Additionally, we analyzed the association between RPS6KA2 expression levels and clinicopathological characteristics from ovarian cancer patients." (PMID 36741009, 2023). "Collectively, these findings suggest that miR-512-3p contributes to cisplatin resistance in ovarian cancer cells by inhibiting apoptosis through negative regulation of RPS6KA2 expression." (PMID 41502518, 2025). "This study seeks to explore the function of RPS6KA2 in reversing cisplatin resistance in ovarian cancer through comprehensive in vivo and in vitro approaches." (PMID 41502518, 2025). "Collectively, these insights underscore the pivotal role of RPS6KA2 in mitigating cisplatin resistance through modulation of key signaling networks in ovarian cancer." (PMID 41502518, 2025). "A high-throughput sequencing comparison between 92 ovarian cancer patients with low RPS6KA2 expression and 96 with high expression identified 617 upregulated and 6 downregulated genes in the high-expression cohort." (PMID 41502518, 2025). "Collectively, these results confirm that miR-512-3p enhances autophagic signaling in ovarian cancer by suppressing RPS6KA2 expression." (PMID 41502518, 2025). "Since ROS production is a hallmark of ferroptosis progression, these findings collectively indicate that RPS6KA2 contributes to the induction and regulation of ferroptosis in ovarian cancer." (PMID 41502518, 2025). "Single-cell sequencing data showed that among various cell types in ovarian cancer tissues, monocytes and macrophages exhibited the highest RPS6KA2 expression, tumor cells displayed moderate levels, while fibrocytes had the lowest expression." (PMID 41502518, 2025). "This study reveals that RPS6KA2 enhances the sensitivity of ovarian cancer cells to cisplatin by suppressing the autophagy signaling pathway, representing a novel and significant contribution to the field." (PMID 41502518, 2025). "In conclusion, the miR-512-3p/RPS6KA2 axis plays a critical role in regulating cisplatin sensitivity in ovarian cancer by coordinately influencing both autophagy and ferroptosis signaling pathway at both in vitro and in vivo levels." (PMID 41502518, 2025). "In vivo validation confirmed that combining RPS6KA2 targeting with autophagy inhibitors or ferroptosis inducers significantly enhanced cisplatin sensitivity in ovarian cancer models." (PMID 41502518, 2025). "This study was designed to explore the therapeutic relevance of modulating RPS6KA2 in the context of ovarian cancer, particularly in relation to cisplatin resistance." (PMID 41502518, 2025). "In ovarian cancer, recent findings show that RPS6KA2 expression is regulated by the non-coding RNA networks involving circFAM169A/miR-106a-5p and miR-519d-3p, which in turn influence the proliferative capacity of ovarian cancer cells." (PMID 41502518, 2025). "More importantly, this study reveals that targeting RPS6KA2 enhances the responsiveness of ovarian cancer cells to cisplatin." (PMID 41502518, 2025). "Using ovarian cancer cell lines and clinical tissue samples, we demonstrated that RPS6KA2 expression was significantly downregulated in cisplatin-resistant cells and tissues compared to their sensitive counterparts." (PMID 41502518, 2025).
ovarian carcinoma (continued). "Collectively, these findings strongly support the role of low RPS6KA2 expression in promoting cisplatin resistance in ovarian cancer." (PMID 41502518, 2025). "What’s more, the expression of RPS6KA2 was positively correlated with circFAM169A in ovarian cancer cells." (PMID 36741009, 2023). "We found that SB203580 and RPS6KA2-Sh synergistically inhibited p38/MAPK phosphorylation in ovarian cancer cells, while SB203580 partially rescued p38/MAPK activation caused by RPS6KA2-OE." (PMID 36741009, 2023). "Then we demonstrated that RPS6KA2 inhibited proliferation in ovarian cancer via p38/MAPK signaling pathway." (PMID 36741009, 2023). "Histochemistry score (H-score) in normal tissues (N) were 13.5 and 3.8 times higher than those in tumor tissues (T), which confirmed a low protein expression of RPS6KA2 in ovarian cancer, especially in cytoplasm." (PMID 36741009, 2023). "In this study, we found that RPS6KA2 showed significant low expression in ovarian cancer tissue and that there was a correlation between the low expression of RPS6KA2 and poor prognosis in ovarian cancer patients." (PMID 36741009, 2023). "We identified RPS6KA2 as the prognosis-related gene of ovarian cancer from TCGA, GSE26712 and GSE26193 database via bioinformatic analysis." (PMID 36741009, 2023). "In contrast, SKOV3 cells transfected with RPS6KA2 shRNA enhanced the proliferation and colony formation capability of ovarian cancer cells." (PMID 36741009, 2023). "GSEA showed RPS6KA2 inhibited cell proliferation and promoted cell apoptosis in ovarian cancer through MAPK signaling pathway." (PMID 36741009, 2023). "We analyzed its mRNA degree of expression in 26 tumor tissues and 17 normal tissues by qRT-PCR, we found that RPS6KA2 mRNA levels were significantly lower in ovarian cancer patient tissues compared to those in normal tissues." (PMID 36741009, 2023). "qRT-PCR and western blot detected the differential expression of RPS6KA2 in normal ovaries and ovarian cancer tissues." (PMID 36741009, 2023). "This was supported by further studies, in which we found that RPS6KA2 was downregulated in ovarian cancer tissues and cell lines and promoted the proliferative capacity of ovarian cancer cells." (PMID 36741009, 2023). "Our data demonstrated that circFAM169A functioned as the ceRNA for miR-106a-5p and miR-519d-3p to facilitate RPS6KA2 expression and inhibit ovarian cancer cell proliferation through p38/MAPK signaling pathway." (PMID 36741009, 2023). "RPS6KA2 expression levels were markedly reduced in ovarian tumor tissues relative to normal controls, implying a potential role in the initiation of ovarian cancer." (PMID 41502518, 2025). "Consistent with this, CCK8 analysis demonstrated that, upon exposure to different concentrations of cisplatin, ovarian cancer cells with low RPS6KA2 expression displayed enhanced cell viability, whereas those with high RPS6KA2 expression showed greater sensitivity and reduced survival." (PMID 41502518, 2025). "While our findings suggest that RPS6KA2 modulates the cisplatin sensitivity in ovarian cancer cells through the regulation of autophagy and ferroptosis, the exact nature of the crosstalk between these two cellular processes remains unclear." (PMID 41502518, 2025). "Furthermore, the potential of RPS6KA2 as a therapeutic target for mitigating cisplatin resistance in ovarian cancer is rigorously assessed." (PMID 41502518, 2025). "To further explore whether RPS6KA2 inhibits the proliferation of ovarian cancer cells, we conducted CCK-8 and colony formation assays." (PMID 36741009, 2023). "The transfection efficiency of RPS6KA2 lentivirus was verified by WB and PCR, and the results showed that RPS6KA2 expression could be effectively manipulated in ovarian cancer cells." (PMID 36741009, 2023). "It suggested that the MAKP signaling pathway may be involved in RPS6KA2-mediated ovarian cancer progression." (PMID 36741009, 2023).
ovarian carcinoma (continued). "To sum up, we confirmed the significant role of RPS6KA2 in ovarian cancer." (PMID 36741009, 2023). "We found the expression of RPS6KA2 was down-regulated in ovarian cancer tissues." (PMID 36741009, 2023). "Moreover, we analyzed the difference in protein expression of RPS6KA2 in tumor and normal tissues using immunohistochemistry (IHC) in the Human Protein Atlas database and our ovarian cancer specimens." (PMID 36741009, 2023). "Finally, we revealed for the first time the biological function of circFAM169A as upstream of RPS6KA2 in ovarian cancer and regulate RPS6KA2 through miR-106a-5p and miR-519d-3p." (PMID 36741009, 2023). "We demonstrated that circFAM169A/miR-106a-5p, miR-519d-3p mediated low expression of RPS6KA2 could affect the proliferation of ovarian cancer cells via p38/MAPK signaling pathway." (PMID 36741009, 2023). "RPS6KA2 was also identified as a cancer suppressor gene in epithelial ovarian cancer." (PMID 34676211, 2021). "Furthermore, this study reveals that RPS6KA2 enhances ferroptosis, indicating that modulation of ferroptosis represents an additional key mechanism by which RPS6KA2 regulates cisplatin sensitivity in ovarian cancer cells." (PMID 41502518, 2025). "However, the precise function of each subtype is poorly known, until now, the function role of RPS6KA2 in ovarian cancer remains unknown." (PMID 36741009, 2023). "RPS6KA2 was the unique prognosis-related gene present in all three datasets, indicating that RPS6KA2 may play an important role in the development and prognosis of ovarian cancer." (PMID 36741009, 2023). "Further studies confirmed that overexpression of circFAM169A can also inhibit the proliferation and cell viability of ovarian cancer through CCK-8 and EdU assay, and inhibition of RPS6KA2 can partially counteract the effects of circFAM169A." (PMID 36741009, 2023). "To investigate the molecular mechanism of RPS6KA2 in ovarian cancer, we conducted gene set enrichment analysis (GSEA) according to the expression level of RPS6KA2." (PMID 36741009, 2023). "In our study, we found RPS6KA2 was related to the prognosis of ovarian cancer through TCGA, GSE26712 and GSE26193, the highly expression of RPS6KA2 had a better prognosis in ovarian cancer." (PMID 36741009, 2023).
pancreatic cancer (6 papers, 2018 to 2025). "RPS6KA2, a serine/threonine protein kinase family member, is substantially overexpressed in several cancer types, including prostate, breast, and pancreatic cancers." (PMID 40098701, 2025). "Rps6ka2 has been reported to function downstream of Erk signal pathway and result in decreased apoptosis in pancreatic cancer." (PMID 29888212, 2018).
prostate carcinoma (5 papers, 2011 to 2025). A carcinoma that arises from epithelial cells of the prostate gland. "Studies have suggested RPS6KA2 is related to the occurrence and development of prostate cancer." (PMID 36741009, 2023). "KS6A2/RPS6KA2, also known as RSK/RSK3, is a member of the RSK serine/threonine-protein kinase family that acts as a downstream effector of ERK in the MAPK1/ERK2 and MAPK3/ERK1 signaling pathway, mediating cellular proliferation and survival in prostate cancer." (PMID 34359681, 2021). "To assess whether other molecules in the prostate cancer cell were affected by the expression of SCIN, we preliminarily used a gene expression chip to screen PC‐3 cells (unpublished data) and found that the EGFR and RPS6KA2 expression was regulated by SCIN." (PMID 29744289, 2018).
rectal cancer (3 papers, 2015 to 2023). A primary or metastatic malignant neoplasm that affects the rectum. "The intersection of the candidate target genes in the MAPK pathway and the overexpressed genes in colon and rectal cancer in TCGA and GTEx was taken, and 5 candidate genes EFNA2, RPS6KA2, MAPK13, EFNA3 and FGFR3 were identified." (PMID 34998382, 2022).
Coffin-Lowry syndrome (2 papers, 2013). A rare X-linked syndromic intellectual disability characterized by global development delay, postnatal growth retardation leading to short stature, facial dysmorphism, short hands with tapering fingers and progressive skeletal abnormalities including kyphoscoliosis and pectus carinatum/excavatum. "RPS6KA2 (RSK3) belongs to a family of four highly homologous proteins encoded by distinct genes related with Coffin-Lowry syndrome." (PMID 23398904, 2013).
glioblastoma (2 papers, 2017 to 2025). The most malignant astrocytic tumor (WHO grade IV). "Of note, RPS6KA2 was also determined to be a downstream target of BMI1 in glioblastoma stem cells." (PMID 28423600, 2017).
glioma (2 papers, 2017 to 2020). A benign or malignant brain and spinal cord tumor that arises from glial cells (astrocytes, oligodendrocytes, ependymal cells). "The RPS6KA2 gene can influence brain network related to attention performance and in glioma tumor formation." (PMID 28792504, 2017).
lung carcinoma (2 papers, 2017 to 2023). "Survival analyses available for breast and lung cancer patients supported this hypothesis as high expression of both DUSP6 and RPS6KA2 were associated with significantly improved survival in both cancer types." (PMID 28423600, 2017).
melanoma (2 papers, 2017 to 2023). A malignant, usually aggressive tumor composed of atypical, neoplastic melanocytes. "Among them, 6 genes (NPTX1, AUTS2, RPS6KA2, KAT2B, MYO5A and HMG20B) were simultaneously downregulated in the melanoma samples compared with the noncancerous samples in GSE31909 and GSE35388 microarray data." (PMID 37384727, 2023).
Obesity (2 papers, 2018 to 2019). Accumulation of substantial excess body fat. "Here, we found that some DMR genes are obesity genes or related to the former which have been studied by genomic and genome-wide association study (GWAS) methods, for example, FTO, PCSK5, PCSK6, NTRK2, ABCC4, TXNIP and RPS6KA2." (PMID 31637123, 2019).
colorectal cancer (1 paper, 2021). A primary or metastatic malignant neoplasm that affects the colon or rectum. "Genetic variation of RPS6KA2 was related to the carcinogenesis of colorectal cancer." (PMID 34676211, 2021).